MOB3A (MOB kinase activator 3A)
Description:
May regulate the activity of kinases.
Synonyms: MOBKL2A; MOB1C; MOB-LAK; moblak
Tractability: PROTAC: ubiquitination databases record sites on it; its protein half-life has been measured.
Gene: Protein-coding gene on chromosome 19 (2,071,032 to 2,096,679, reverse strand). Ensembl gene ENSG00000172081.
Subcellular location (Human Protein Atlas): Cytosol; Intermediate filaments
Gene Ontology:
Molecular function: protein kinase activator activity
Genetic constraint (gnomAD): Loss-of-function variants: 17 observed, 18.23 expected, observed/expected ratio (o/e) 0.93, 90% interval 0.64 to 1.4. The upper end of that interval is the gene's LOEUF score, 1.4, which puts it in group 5 of 6, group 1 being the genes least tolerant of losing a copy. Missense variants: 333 observed, 322.8 expected, observed/expected ratio (o/e) 1.03, 90% interval 0.94 to 1.13. Synonymous variants: 124 observed, 136.87 expected, observed/expected ratio (o/e) 0.91, 90% interval 0.78 to 1.05.
Homologues: Orthologues: chimpanzee MOB3A (100% identical), dog MOB3A (96% identical), macaque MOB3A (96% identical), rat Mob3a (95% identical), mouse Mob3a (94% identical), pig MOB3A (93% identical), guinea pig MOB3A (92% identical), tropical clawed frog mob3a (89% identical), zebrafish mob3a (84% identical), Drosophila melanogaster Mob3 (65% identical), Caenorhabditis elegans mob-3 (62% identical). Paralogues in human: MOB3B (81% identical), MOB3C (73% identical), MOB1B (53% identical), MOB1A (52% identical), MOB2 (34% identical), MOB4 (22% identical).
Diseases named in the same sentence as MOB3A in open-access papers:
MOB3A is named in the same sentence as 3 diseases in open-access papers, as found by Europe PMC text mining. Sharing a sentence is not in itself a finding about the gene and the disease. The quoted sentences say what the papers report.
glioblastoma (1 paper, 2023). The most malignant astrocytic tumor (WHO grade IV). "MOB3A and MOB3C are upregulated in gliomas, and combined depletion of all three human MOB3 proteins halted the proliferation of a glioblastoma cell line in vitro and in vivo." (PMID 37536630, 2023).
MOB3A also shares sentences with these, for which no sentence is quoted: glioma (1 paper); tumor (1).